LGALS9 (galectin 9)
Diseases named in the same sentence as LGALS9 in open-access papers (continued):
Sharing a sentence is not in itself a finding about the gene and the disease.
colon carcinoma (continued). "Our results show that although the majority of colon cancer cells express galectin-9, both the positive rate and the level of expression are lower in these tissues than in normal colon tissues." (PMID 27028892, 2016). "Based on the median of the observed levels of galectin-9, the colon tumor patients were divided into low (0–1, n = 39) and high (2–4, n = 51) expressing groups." (PMID 27028892, 2016). "In conclusion, these data provided the first evidence that galectin-9 is down-regulated in colon tumor tissue and suggests a poor outcome." (PMID 27028892, 2016). "In the present study, we demonstrated that galectin-9 expression is lower in colon tumor tissue than in corresponding normal tissues and galectin-9 levels are associated with NK cell infiltration and patient survival." (PMID 27028892, 2016). "In these experiments, we determined the level of galectin-9 expression in 3 colon cancer cell lines, including SW480, SW620 and HT29, using qRT-PCR and western blot analysis." (PMID 27028892, 2016). "We have therefore identified a new mechanism by which galectin-9 influences NK cell recruitment during colon tumor development, and this increases our current knowledge of the molecular involvement of galectin-9 in tumor immunity." (PMID 27028892, 2016). "Indeed, the targeted deletion of ATXN3 in human colon cancer cells, leading to a substantial reduction in Galectin-9, markedly intensified both HCT116 and MC38 colon cancer cell proliferation." (PMID 38815863, 2024). "Investigating whether the oncogenic miR-25 inhibits Galectin-9 in colon cancers presents an intriguing avenue for future research." (PMID 38815863, 2024). "Therefore, a strong positive correlation between ATXN3 and Galectin-9 protein in human colon cancer tissues was detected." (PMID 38815863, 2024). "Subsequently, we analyzed ATXN3 and Galectin-9 expression levels in human colon cancers." (PMID 38815863, 2024). "Additionally, flow cytometry analysis revealed a significant reduction in colon cancer cell death upon ATXN3 ablation, with Galectin-9 expression reversing the apoptosis of ATXN3-null colon cancer cells." (PMID 38815863, 2024). "Furthermore, immunohistochemistry staining revealed a significant reduction in both ATXN3 and Galectin-9 protein expression, along with a positive correlation between them in human colon cancer." (PMID 38815863, 2024). "Consequently, targeted ATXN3 ablation resulted in reduced Galectin-9 protein expression, thereby diminishing Galectin-9-induced colon cancer apoptosis and cell growth arrest." (PMID 38815863, 2024). "The ectopic expression of Galectin-9 fully reversed the growth of ATXN3-null colon cancer in mice." (PMID 38815863, 2024). "Notably, miR-455-5p promotes tumor growth by targeting galectin-9 and inhibiting apoptosis in colon cancer." (PMID 37047155, 2023). "In colon tumors, however, infiltrating immune cells appears to be a major source of PD-L1 and PD-L2, as well as Galectin-9, and may thus modify MAIT cell function in human colorectal cancer." (PMID 33885944, 2021). "We explored the prognostic value of galectin-9 in colon cancer." (PMID 27028892, 2016). "Together with our findings in colon cancer tissues, these data suggest that galectin-9 might be involved in the recruitment of NK cells." (PMID 27028892, 2016). "However, little is known about the details relating to the expression of galectin-9 in colon cancer tissues." (PMID 27028892, 2016). "The role of galectin-9 as a chemoattractant for NK cells was partially demonstrated by our in vitro transwell studies, which showed that both colon cancer cell-derived galectin-9 and rh-galectin-9 enhanced the migratory properties of NK cells, whether they are NK-92 or primary NK cells." (PMID 27028892, 2016). "In contrast, CD27, CD276, LAG3, LGALS9, PDCD1, and TMIGD2 showed a highly enriched trend of expression with RFX1 in colon cancer." (PMID 41425715, 2025).
colon carcinoma (continued). "Flow cytometry analysis confirmed similar levels of Galectin-9 expression in the stably expressed ATXN3 WT and KO colon cancer cells." (PMID 38815863, 2024). "Furthermore, Galectin-9 has been recognized as a crucial positive regulator of mucosal immunity in combatting gut inflammation caused by the microbiome through the Th17-IgA axis, establishing an additional connection for ATXN3 in suppressing inflammation-induced colon cancer." (PMID 38815863, 2024). "Our study identifies the first Galectin-9-specific deubiquitinase and unveils a tumor-suppressive role of ATXN3 in human colon cancer." (PMID 38815863, 2024). "Our study establishes ATXN3 as the inaugural Galectin-9-specific deubiquitinase and brings to light a tumor-suppressive role of ATXN3 in human colon cancer." (PMID 38815863, 2024). "However, because the presence and significance of galectin-9 expression has not yet been demonstrated in colon cancer tissues, it remains unclear whether this association occurs in colon cancer and what regulatory mechanisms are involved, if any." (PMID 27028892, 2016). "Subsequently, we established stable expression of Galectin-9 in ATXN3 wild-type and KO colon cancer cells to investigate whether reintroducing Galectin-9 expression could mitigate the heightened tumor progression observed upon ATXN3-targeted suppression." (PMID 38815863, 2024). "Consistently, ATXN3 protein was identified through Western blotting in anti-Galectin-9 immunoprecipitants but not in normal rabbit IgG controls from HCT116 colon cancer cells." (PMID 38815863, 2024). "Peptide P26 blocks the interaction between TIM-3 and its ligand galectin-9 (Gal-9) so as to reverse Gal-9-inhibited T cell activation and to trigger T-cell and cytokines-dependent anticancer effects in an MC38 model of murine colon cancer." (PMID 34944985, 2021). "Conversely, the absence of ATXN3 expedited the degradation of Galectin-9 in colon cancer cells." (PMID 38815863, 2024). "Moreover, the median immunohistochemistry score for galectin-9 was lower in the colon carcinoma samples than in in the normal mucosal samples (P<0.001)." (PMID 27028892, 2016).
glioblastoma (30 papers, 2015 to 2026). The most malignant astrocytic tumor (WHO grade IV). "Within this family, LGALS1, LGALS3, and LGALS9 have been most consistently implicated in glioblastoma progression, through roles in tumour proliferation, immune evasion, and resistance to therapy." (PMID 41516291, 2025). "Consistent with our UALCAN analysis, LGALS1, LGALS3, and LGALS9 were also overexpressed in glioblastoma." (PMID 41516291, 2025). "Our study highlights the role of LGALS1, LGALS3, and LGALS9 in glioblastoma invasion and migration via the induction of T cell apoptosis, protein homeostasis, and the maintenance of the ECM." (PMID 41516291, 2025). "A study by Ni and colleagues demonstrated that patients with glioblastoma tumors that displayed high expression scores for galectin-9 and TIM-3 had significantly lower survival than patients with tumors with low expression scores of galectin-9 and TIM-3." (PMID 40072074, 2025). "This study provides a comprehensive, family-wide analysis of galectins in glioblastoma, revealing that LGALS1, LGALS3, and LGALS9 are consistently overexpressed and strongly associated with adverse survival, immune dysregulation, and tumour-promoting pathways." (PMID 41516291, 2025). "Compared to normal brain tissues, LGALS1, LGALS3, and LGALS9 were significantly overexpressed in glioblastoma samples, with LGALS9 exhibiting the highest transcript abundance." (PMID 41516291, 2025). "Complementing these tumour-intrinsic mechanisms, LGALS9 appears to play a pivotal role in immune evasion and immunosuppression in the glioblastoma microenvironment, consistent with emerging evidence from recent immunogenomic studies." (PMID 41516291, 2025). "We identified LGALS1, LGALS3, and LGALS9 as significantly upregulated in glioblastoma, with their overexpression correlating with adverse patient survival." (PMID 41516291, 2025). "Together, these data and our current findings underscore LGALS9 as a key regulator of immune escape in glioblastoma and reinforces its promise as a prognostic marker and potential therapeutic target." (PMID 41516291, 2025). "T7 peptide is modified on 293T cells, and its exosomes are used to deliver Galectin-9 siRNA, which can promote macrophage repolarization and inhibit the immunosuppression of glioblastoma (GBM)." (PMID 38633106, 2024). "LGALS9, a specific protein cargo contained in Glioblastoma-CSF-EVs, was shown to inhibit the antigen presentation of dendritic cells and cytotoxic T cell (CD8+) immunity, promoting tumor progression." (PMID 38379858, 2024). "Among protein upregulated in glioblastoma small EVs, authors found Galectin 9 (LGALS9), the ligand of the DC-expressed immune checkpoint T-cell immunoglobulin and mucin domain 3 (TIM3)." (PMID 39075551, 2024). "Experiment in LGALS9 knockout mice showed sustained tumor antigen-presenting activity and long-lasting immunity against glioblastoma." (PMID 39075551, 2024). "Binding of galectin 9 (LGALS9) expressed on EVs derived from glioblastoma multiforme (GBM) cells to the TIM3 receptor of DCs affects antigen recognition, processing and presentation, leading to inhibition of cytotoxic T cell-mediated anti-tumor responses." (PMID 36498469, 2022). "Galectin-9 on glioblastoma-derived EVs binds to the TIM3 DCs receptor and inhibits antigen presentation by DCs, leading to disrupted antitumor immune responses of cytotoxic T cells." (PMID 36612080, 2022). "We attempted to compare the levels of LGALS9 transcription and translation between malignant glioblastoma lines (U118 MG and U87 MG) and primary astrocytes (HA)." (PMID 33093453, 2020). "Another study showed that exosomes from the cerebral spinal fluid of glioblastoma patient contained galectin-9, which could hinder antigen recognition, processing, and presentation by dendritic cells (DCs) in a TIM-3-dependent mechanism." (PMID 40072074, 2025).
glioblastoma (continued). "Recent studies showed that glioblastoma-derived exosomal LGALS9 suppresses dendritic cell (DC) antigen presentation and cytotoxic T cell immunity in cerebrospinal fluid (CSF), providing a mechanistic basis for the profound immune dysfunction observed in glioblastoma." (PMID 41516291, 2025). "Furthermore, a prior clinical study has shown that higher LGALS9 expression in glioblastoma correlates with reduced survival outcomes, suggesting its potential as a prognostic biomarker." (PMID 41516291, 2025). "Alternatively, whether another key molecule other than galectin-9 can directly or indirectly regulate TIM-3 expression in the glioblastoma setting is open for speculation and requires further study." (PMID 39513882, 2024). "For example, in a recent report, Li and colleagues used galectin-9-specific siRNA loaded into exosomes decorated with transferrin receptor-binding peptides to target glioblastoma cells and inhibit their growth, opening the way to novel immunotherapies of glioblastoma." (PMID 37753083, 2023). "Glioblastoma multiforme-derived exosome LGALS9 can play a significant regulatory role in tumor progression by inhibiting dendritic cell antigen presentation and cytotoxic T cell activation in CSF; if this inhibition is lost, it can lead to long-lasting systemic anti-tumor immunity." (PMID 36797708, 2023). "Likewise, the exosomes isolated from the cerebrospinal fluid (CSF) of the patients with glioblastoma multiforme (GBM) have also been shown to contain higher amounts of Galectin-9." (PMID 34078376, 2021). "Another study shows that exosomes acquired from the cerebrospinal fluid (CSF) of glioblastoma multiforme (GBM), one of the most aggressive and common brain tumors, contained Galectin-9, which is a molecule involved in preventing DC cell maturation." (PMID 41142789, 2025). "Interestingly, galectin-9 (and HMGB1) is elevated in glioblastoma tumor tissue, suggesting that persistent long-term stimulation with galectin-9 may be required for enhanced TIM-3 expression." (PMID 39513882, 2024). "For example, LGALS9, which is a unique protein contained in exosomes from the CSF of glioblastoma patients, contributes to the inhibition of antitumor immunity and could be an effective indicator of glioblastoma and chemoresistance." (PMID 35986010, 2022). "Mechanistically, they showed that PTEN null glioblastoma cells secreted higher levels of the TIM-3 ligand, galectin-9, leading to a TIM-3-dependent polarization of M2 macrophages." (PMID 40072074, 2025). "In glioblastoma, a tumor suppressor gene, the phosphatase and tensin homolog (PTEN) gene, is deleted, leading to increased secretion of galectin-9 (Gal-9), which induces polarization of TAMs toward the M2 type." (PMID 40850976, 2025). "Nasopharyngeal carcinoma-derived vesicular galectin-9 induced apoptosis in CD4+ T cells via interaction with Tim-3, as well as impairing T-cell function by interaction with TIM3 receptor on DCs in glioblastoma." (PMID 36612080, 2022). "LGALS9 (galectin-9) acts as the ligand for the T cell immunoglobulin domain and mucin domain-3 on CD4+ T cell surface, thereby leading to T cell apoptosis and poor prognosis in glioblastoma." (PMID 38379858, 2024). "This depends on the enhanced expression of PD-L1, but no other immune checkpoint genes, such as B7-H3, herpesvirus entry mediator (HVEM), and galectin-9 (LGALS9), suggesting that TMZ controls the expression of PD-L1 in glioblastoma cells, resulting in the evasion of the immune system." (PMID 31653034, 2019). "We also found that the transcription factor CCAAT enhancer-binding protein alpha (CEBPA), located on chromosome 19q, played a key role in regulating the expression level of Galectin-9 in both lower-grade glioma (LGG) and glioblastoma (GBM)." (PMID 34956239, 2021).
glioblastoma (continued). "In vitro, long noncoding RNA H19 (H19-IRP) promotes glioblastoma multiforme (GBM) immunosuppression by binding to CCL2 and galectin-9 promoters to activate its transcription and recruiting myeloid-derived suppressor cells (MDSCs) and TAMs to induce T cell exhaustion and an immunosuppressive GBM-TME." (PMID 41341593, 2025).
lupus (27 papers, 2013 to 2025). "Galectin-9 administration attenuates kidney disease severity in murine lupus models by suppressing toll-like receptor 7–mediated activation of plasmacytoid dendritic cells and B cells." (PMID 40904455, 2025). "Similar to their discovery of IFN-responsive monocyte subsets in lupus, our work uncovers injury-specific macrophage subpopulations (e.g., Lgals9+ macrophages) driving neuro-immune crosstalk." (PMID 40993792, 2025). "Yuksel K, Sag E, Demir S, Özdel S, Kaya UA, Atalay E, Cuceoglu MK, Topaloglu R, Bilginer Y, Ozen S. Plasma checkpoint protein levels and galectin-9 in juvenile systemic lupus erythematosus." (PMID 37848930, 2023). "Again independently of Tim-3, galectin-9 has been shown to ameliorate clinical severity of lupus-prone MRL/lpr mice by inducing plasma cell apoptosis." (PMID 26076826, 2015). "Collectively, it is likely that galectin-9 attenuates the clinical severity of MRL lupus-prone mice by regulating T cell function and inducing plasma cell apoptosis." (PMID 23585851, 2013). "Although anti-dsDNA antibody was increased in MRL/lpr lupus-prone mice, galectin-9 suppressed anti-dsDNA antibody production, at least partly, by decreasing the number of plasma cells." (PMID 23585851, 2013). "In this prospective study, we aimed to investigate the association of serum (s) and urine (u) IP-10, galectin-9, and SIGLEC-1 with disease activity in patients with systemic lupus erythematosus (SLE)." (PMID 39050398, 2024). "The present experiment shows that galectin-9 ameliorates a variety of clinical symptoms, such as proteinuria, arthritis, and hematocrit in MRL/lpr lupus-prone mice." (PMID 23585851, 2013). "However, there had also been experiments showing that the intervention of lupus-prone mice with intraperitoneal galectin-9 could ameliorate their proteinuria and arthritis by decreasing the anti-dsDNA antibody levels, likely through the pro-apoptotic effect of galectin-9 on plasma cells." (PMID 31597242, 2019). "For instance, in systemic lupus erythematosus (SLE), IL15 (interleukin-15) and LGALS9 (galectin-9) were shown as the most useful features in the prediction." (PMID 39897058, 2025). "Although about 20% of CD19−/low CD138+ plasma cells expressed Tim-3 in MRL/lpr lupus-prone mice, Tim-3 may not be directly involved in the galectin-9-induced apoptosis, because anti-Tim-3 blocking antibody did not block galectin-9-induced apoptosis." (PMID 23585851, 2013). "Studies on the functional role of galectin-9 in human SLE are lacking, and data from lupus mouse models show divergent results." (PMID 34276678, 2021). "Furthermore, treatment with galectin-9 induces apoptosis in plasma cells purified from MRL/lpr lupus-prone mice, and the effect cannot be prevented with anti-Tim-3 monoclonal antibodies (mAb); this suggests the involvement of a non-Tim-3 receptor for galectin-9-mediated apoptosis in plasma cells." (PMID 28991189, 2017).
Autoimmunity (26 papers, 2011 to 2025). The occurrence of an immune reaction against the organism's own cells or tissues. "Galectin-9 (coded by LGALS9 gene) is a crucial regulator of T cell immunity by inducing apoptosis in specific T cell subpopulations associated with autoimmunity and inflammatory disease." (PMID 36077273, 2022). "Here, we demonstrate a critical role for the glycan-binding protein galectin-9 in setting the threshold of B cell activation and that loss of this regulatory network is sufficient to drive spontaneous autoimmunity." (PMID 34369876, 2021). "Galectin-9 (Gal-9) seems to be a crucial regulator of T-cell immunity by inducing apoptosis in specific T-cell subpopulations associated with autoimmunity and inflammatory disease." (PMID 33250901, 2020). "Because galectin-9 controlled Th1 effector cells we determined whether it could also control the pathogenic CD4loCD40+ T cells in autoimmunity." (PMID 22685601, 2012). "Previous studies have revealed that Galectin-9 (Gal-9) acts as an apoptosis modulator in autoimmunity and rheumatic inflammation." (PMID 38957462, 2024). "Recent studies have shown that LGALS9 signaling regulates autoimmunity through Tim-3, accompanied by promoting macrophage phenotypic transition to anti-inflammatory type, increasing the number of Tregs, and decreasing in numbers of effector T cells." (PMID 35990248, 2022). "The interaction between TIM-3 and galectin 9 has been demonstrated to induce Th1 cell apoptosis, leading to reduced responses from autoimmunity and antitumor immunity and also making TIM-3 as a potential target for ICB." (PMID 33062039, 2020). "The interaction between T-cell immunoglobulin mucin (TIM)-3 and Galectin-9 (Gal-9) mediates signaling pathways involved in infection, autoimmunity, inflammation, peripheral tolerance, and tumor immunity." (PMID 25886742, 2015). "We also demonstrate that higher concentrations of galectin-9 induce cell death in NOD CD4loCD40+ T cells, suggesting a mechanism to control these pathogenic cells in autoimmunity." (PMID 22685601, 2012). "Galectin-9 (Gal-9) is known for induction of apoptosis in IFN-γ and IL-17 producing T-cells and amelioration of autoimmunity in murine models." (PMID 23741502, 2013).